CPA4 (carboxypeptidase A4)
Diseases named in the same sentence as CPA4 in open-access papers (continued):
Sharing a sentence is not in itself a finding about the gene and the disease.
glioma (7 papers, 2019 to 2025). A benign or malignant brain and spinal cord tumor that arises from glial cells (astrocytes, oligodendrocytes, ependymal cells). "This ceRNA mechanism leads to the upregulation of CPA4 expression and ultimately poor survival outcomes in gliomas." (PMID 40805261, 2025). "circ_0082375 (hsa_circCPA4_007), derived from the CPA4 gene, was first identified to be significantly increased in glioma by high-throughput circRNA microarray assay." (PMID 34868669, 2021). "Next, we explored the clinical significance of CPA4 in glioma and found that high CPA4 expression (35/73) was related to poor outcome of glioma." (PMID 31424161, 2019). "Through the competitive endogenous RNA (ceRNA) mechanism, circCPA4 sponges let‐7 to regulate the expression of CPA4 and glioma progression." (PMID 31424161, 2019). "However, in gliomas, their interaction is competitively inhibited by circular CPA4 RNA (circCPA4), which acts as a competitive endogenous RNA (ceRNA)." (PMID 40805261, 2025). "The CircCPA4 sponge let-7 regulates the expression of CPA4 and glioma progression." (PMID 34827136, 2021). "For instance, circCPA4, which is highly expressed in glioma tissues and positively related to poor outcome of glioma, could act as a sponge for let-7 to regulate the expression of CPA4 and glioma progression." (PMID 33407501, 2021). "The circCPA4/let‐7/CPA4 axis regulates glioma progression by ceRNA mechanism, and circCPA4 could be a novel biomarker and target for glioma treatment." (PMID 31424161, 2019). "Survival analysis revealed that high levels of CPA4 were related to poor outcome of glioma." (PMID 31424161, 2019). "The circCPA4/let‐7/CPA4 axis regulates glioma progression by ceRNA mechanism, and circCPA4 could be a novel prognostic biomarker and target for glioma treatment." (PMID 31424161, 2019). "CircCPA4 could regulate the proliferation and metastasis of glioma, and regulate CPA4 expression through sponging let‐7 in glioma." (PMID 31424161, 2019). "hsa_circ_0082375 (chr7: 129950626–129964020), derived from the carboxypeptidaseA4 (CPA4) gene, has been uncovered to be upregulated in glioma tissues of 73 patients, whereas the underlying mechanism of hsa_circ_0082375 in glioma has not been clearly explained yet." (PMID 34868669, 2021). "The other well-predicted genes, including COL5A1, CPA4, CSTB, and PPIC in gliomas and DAK, ITPRIP, TM4SF19, TMEM200A in RCC have not been studied thoroughly in cancer and their roles in cancer worth further investigating." (PMID 32194984, 2020).
colorectal cancer (6 papers, 2016 to 2025). A primary or metastatic malignant neoplasm that affects the colon or rectum. "CPA4 expression was also found in about two-thirds (130/190) of colorectal cancer tissues, which significantly correlated with invasion, lymph node metastasis, as well as distal metastasis." (PMID 40805261, 2025). "Carboxypeptidase A4 (CPA4) is a zinc-dependent metallocarboxypeptidase that is overexpressed in various cancer tissues, including colorectal cancer (CRC), which is in line with the results of the present study." (PMID 39028420, 2024). "CPA4 positivity was observed in 68.4% (130/190) colorectal cancer tissues, and significantly correlated with Depth of invasion, Lymph node metastasis, Distant metastasis and Stage." (PMID 27780921, 2016). "In this study, we examined CPA4 level in primary colorectal cancer tissue and serum samples, and analyzed the correlation between CPA4 levels and clinicopathological characteristics of CRC patients." (PMID 27780921, 2016). "Kaplan-Meier survival analysis showed that increased CPA4 concentrations of 3500 pg/mL or higher in colorectal cancer serum were correlated with poor overall survival (P = 0.000)." (PMID 27780921, 2016). "The results indicated that high CPA4 expression was observed in 68.4% (130/190) colorectal cancer samples, and significantly correlated with depth of invasion, lymph node metastasis, distant metastasis and Stage." (PMID 27780921, 2016). "Until now little is known about the expression of CPA4 in colorectal carcinoma tissues and its predictive value for liver metastasis." (PMID 27780921, 2016). "Future studies could evaluate the inhibition of these pathways to mitigate CPA4 overexpression in colorectal cancer." (PMID 40805261, 2025). "Similarly, the concentration of CPA4 in serum was significantly increased in CRC patients, and higher serum CPA4 levels were correlated with poor prognosis and liver metastasis in colorectal cancer patients." (PMID 40805261, 2025). "Furthermore, serum CPA4 level combining with Lymph node metastasis may be used as accurate predictors of liver metastasis in colorectal cancer." (PMID 27780921, 2016). "Therefore, our results suggest that CPA4 is closely associated with CRC liver metastasis, and serum CPA4 concentration combined with lymph node involvement may be used as accurate predictors of liver metastasis in colorectal cancer." (PMID 27780921, 2016). "Despite the important clinical significance of CPA4 in many types of cancer, no previous studies have examined the level of CPA4 in colorectal cancer tissue and serum samples, and studied its predictive value for liver metastasis." (PMID 27780921, 2016).
lung carcinoma (5 papers, 2019 to 2025). "Nevertheless, the overexpression of CPA4 has been associated with the progression and aggressiveness of many malignancies, including prostate, pancreatic, breast and lung cancer, to name a few." (PMID 40805261, 2025). "A study demonstrated gene amplification and an increase in CPA4 levels of lung cancer tissues when compared with normal lung tissue, which correlated with poor prognosis." (PMID 40805261, 2025). "Their analysis of three Oncomine datasets demonstrated increased CPA4 gene copy number in lung cancer tissues than normal lung tissues in TCGA and Weiss datasets and upregulation of CPA4 mRNA in the Hou lung dataset." (PMID 40805261, 2025). "CPA4 knockdown has been reported to inhibit lung cancer cell proliferation by inducing cell cycle G1 arrest, downregulation of Cyclin D1 and apoptosis." (PMID 37162264, 2023). "CPA4 downregulation significantly reduced lung cancer cell LTT proliferation, colony-formation assays in soft agar and mammosphere formation in serum-free medium." (PMID 33746592, 2021). "Our previous studies firstly demonstrated that CPA4 was over-expressed in pancreatic, liver, esophageal and lung cancer tissues." (PMID 33746592, 2021). "To confirm this result, we expanded the number of lung cancer tissues to evaluate CPA4 protein expression by immunohistochemistry." (PMID 31397502, 2019). "Together, these results indicate that CPA4 knockdown inhibits lung cancer cells growth by inducing G1‐S arrest and cell apoptosis." (PMID 31397502, 2019). "In this study, we demonstrated that CPA4 depletion suppressed lung cancer growth in vitro and in vivo." (PMID 31397502, 2019). "Our work revealed that CPA4 was overexpressed in most human lung cancer tissues, and decreasing CPA4 inhibited lung cancer growth by inducing apoptosis and G1‐S arrest." (PMID 31397502, 2019). "To explore the function of CPA4 in lung cancer, we generated CPA4 knockdown cells by transducing CPA4 shRNAs into H1299 and A549 cells." (PMID 31397502, 2019). "The result showed that CPA4 protein level was significantly overexpressed in lung cancer cells compared with that in lung normal epithelial cell Beas‐2B." (PMID 31397502, 2019). "Taken together, these results suggest that CPA4 enhances lung cancer growth via the AKT/c‐MYC pathway." (PMID 31397502, 2019). "Lung Cancer: Different groups have studied the role and significance of CPA4 in lung tumorigenesis." (PMID 40805261, 2025). "Another group confirmed that CPA4 promotes lung cancer cell growth and may act via AKT-c-MYC pathway activation through AKT phosphorylation." (PMID 40805261, 2025). "Conversely, ectopic expression of CPA4 enhanced lung cancer cell proliferation." (PMID 31397502, 2019). "We also explored how CPA4 regulates lung cancer cell proliferation and apoptosis." (PMID 31397502, 2019). "Our work indicates that CPA4 plays an oncogenic role in lung cancer." (PMID 31397502, 2019). "Our study revealed that CPA4 expression was higher in both lung cancer cells and tumor tissues." (PMID 31397502, 2019). "Similarly, the results indicated that decreased CPA4 led to an inhibition of lung cancer cell growth." (PMID 31397502, 2019). "We first examined CPA4 expression in lung cancer cells and lung normal epithelial cells." (PMID 31397502, 2019). "Knockdown of c‐MYC in CPA4‐overexpressing cells blocked the increase of Bcl‐2 and restored the expression of P27, indicating that c‐MYC may be the cause of CPA4 promoting lung cancer growth." (PMID 31397502, 2019). "Overall, these data indicated that downregulation of CPA4 inhibits lung cancer growth in vivo." (PMID 31397502, 2019). "Taken together, these results indicate that CPA4 promotes lung cancer cells growth." (PMID 31397502, 2019). "We demonstrated that CPA4 knockdown suppressed lung cancer growth in vitro and in vivo." (PMID 31397502, 2019). "We identified that CPA4 expression was increased in lung cancer cells and most tumor tissues." (PMID 31397502, 2019).
lung carcinoma (continued). "Interestingly, the upregulation of CPA4 led to apoptosis in gefitinib-resistant lung cancer cells and may restore sensitivity in such cases." (PMID 40805261, 2025). "Thus, c‐MYC is required for CPA4 to promote lung cancer cell growth." (PMID 31397502, 2019). "To further validate these novel players in lung cancer cell migration, we selected five candidates—DSE, CPA4, FLNC, TUBB6, and BICC1—and the positive control CDH2, which were upregulated in fast cells and also associated with poor overall survival in NSCLC patients." (PMID 33934493, 2021). "Colony‐formation assays revealed that CPA4 depletion (shCPA4) dramatically reduced the clonogenicity of lung cancer cells compared with nontargeted (shCtrl) cells." (PMID 31397502, 2019).
esophageal squamous cell carcinoma (4 papers, 2019 to 2025). Esophageal squamous cell carcinoma (ESCC) is a type of esophageal carcinoma (EC) that can affect any part of the esophagus, but is usually located in the upper or middle third. "It is reported that CPA4 might be used as an independent poor prognostic factor in esophageal squamous cell carcinoma." (PMID 34827136, 2021). "In esophageal squamous cell carcinoma (ESCC), high expression of CPA4 was found in 58% (87/150) samples, which were significantly associated with histologic grade, lymph node metastasis, and TNM stage." (PMID 40805261, 2025).
hepatocellular carcinoma (4 papers, 2020 to 2022). A malignant tumor that arises from hepatocytes. "CPA4 expression inhibited the tumor proliferation and regulated the expression of stem cell characteristics in hepatocellular carcinoma." (PMID 35686102, 2022). "In hepatocellular carcinoma, AC10364 inhibited cell proliferation and viability through the abnormal expression of genes including CPA4 associated with tumorigenesis or growth." (PMID 34827136, 2021).
bladder cancer (3 papers, 2021 to 2025). "Other Cancers: CPA4 also plays crucial role in other cancers, including endometrial cancers, clear cell renal cell carcinoma (ccRCC), bladder cancer and anaplastic thyroid cancer (ATC)." (PMID 40805261, 2025). "Compellingly, we unraveled that several infiltrating immune cells (Th1cell, Th2 cell, T cell exhaustion, and TAM) were correlated with the expression of CPA4 in bladder cancer using TIMER2 and GEPIA2." (PMID 34827136, 2021). "Moreover, we found that several infiltrating immune cells (Th1cell, Th2 cell, T cell exhaustion, and Tumor-associated macrophage) were correlated with the expression of CPA4 in bladder cancer using TIMER2 and GEPIA2." (PMID 34827136, 2021). "However, no previous research has linked CPA4 to therapeutic or prognostic significance in bladder cancer." (PMID 34827136, 2021). "Moreover, CPA4 plays a specific role in immune infiltration in bladder cancer." (PMID 34827136, 2021). "Despite the potential significance of CPA4 expression in plenty types of cancer, no previous studies have ever shown the expression levels of CPA4 in bladder cancer, especially with regard to its potential therapeautic and prognostic values." (PMID 34827136, 2021).
cardiac hypertrophy (3 papers, 2020 to 2025). "CPA4 facilitates the development of cardiac hypertrophy by activating the PI3K-AKT-mTOR signaling pathway." (PMID 32347291, 2020). "In the present study, we authors aimed to investigate the biological roles of CPA4 in cardiac hypertrophy in humans and rodents." (PMID 32347291, 2020). "Nevertheless, CPA4 was found to be a key regulator of cardiac hypertrophy through activating PI3K-AKT-mTOR signaling and may serve as a promising therapy target for hypertrophic cardiac diseases." (PMID 35686102, 2022). "The expression of CPA4 was overexpressed in human and mouse cardiac hypertrophy." (PMID 32347291, 2020). "Here we demonstrated that CPA4 was an important regulator for cardiac hypertrophy across species." (PMID 32347291, 2020). "Here we attempted to determine the roles of CPA4 in cardiac hypertrophy in humans and rodents." (PMID 32347291, 2020). "In the present study, we investigated the roles of CPA4 in cardiac hypertrophy." (PMID 32347291, 2020). "To this purpose, we initially monitored the expression changes in CPA4 during cardiac hypertrophy." (PMID 32347291, 2020). "Thus, CPA4 contributes to cardiac hypertrophy by activating the PI3K-AKT-mTOR pathway." (PMID 40002810, 2025). "Therefore, we identified CPA4 as a new upstream regulator of the mTOR pathway and CPA4 may serve as a potential therapeutic target for cardiac hypertrophy." (PMID 32347291, 2020). "Here we identified the roles of CPA4 in regulating PI3K-AKT-mTOR signaling and promotes cardiac hypertrophy." (PMID 32347291, 2020). "However, the roles of CPA4 in cardiac hypertrophy remains unknown." (PMID 32347291, 2020). "Herein the present study, we identified CPA4 as an indirect upstream activator for the mTOR-S6K1 signaling pathway and activated mTOR during cardiac hypertrophy." (PMID 32347291, 2020). "Carboxypeptidase A4 (CPA4), a novel upstream regulator of mTOR, is significantly upregulated in isoprenaline (ISO)-induced cardiac hypertrophy in mice, promoting hypertrophy by enhancing PI3K-AKT signaling and activating mTOR and downstream S6K1 phosphorylation." (PMID 40002810, 2025). "Collectively, these results demonstrated that CPA4 is a regulator of cardiac hypertrophy by activating the PI3K-AKT-mTOR signaling, and CPA4 may serve as a promising target for the treatment of hypertrophic cardiac diseases." (PMID 32347291, 2020).
liver cancer (3 papers, 2019 to 2025). An epithelial or non-epithelial malignant neoplasm that arises from the liver. "57/100 (57%) liver cancer samples expressed elevated levels of CPA4, and the increased expression of CPA4 significantly correlated with grade, stage and liver cancer stem cell marker CD90." (PMID 40805261, 2025). "Liver Cancer: CPA4 could play a significant role in liver tumorigenesis and cancer stem cell proliferation." (PMID 40805261, 2025). "Both CPA4 and CD90 could serve as independent predictive factors of poor prognosis in hepatic cancer." (PMID 40805261, 2025).
Lymph node metastasis (2 papers, 2016 to 2021). "CPA4 levels were elevated in 32.1% of the breast tissue samples (45/140), and positive staining for CPA4 was statistically significantly associated with lymph node metastasis and stage." (PMID 33746592, 2021). "Further analysis revealed that CPA4 expression was significantly associated with depth of invasion (P = 0.023), lymph node metastasis (P = 0.043), distant metastasis (P = 0.045) and clinical stage (P = 0.022)." (PMID 27780921, 2016). "This analysis revealed that CPA4 and Lymph node metastasis yielded the most satisfactory sensitivity (95.6%) and specificity (91.8%)." (PMID 27780921, 2016). "This analysis revealed that CPA4 combining with Lymph node metastasis (N) achieved the most satisfactory sensitivity (95.6%) and specificity (91.8%)." (PMID 27780921, 2016). "Both the CPA4 level and Lymph node metastasis showed predictive significance (P < 0.05) and increased the metastatic ratio." (PMID 27780921, 2016). "Logistic regression analysis revealed that serum CPA4 level and Lymph node metastasis were the significant parameters for predicting CRC liver metastasis." (PMID 27780921, 2016). "The odds ratios of CPA4 and Lymph node metastasis were 181.44 and 30.677, respectively." (PMID 27780921, 2016). "Statistical analysis also indicated that positive staining for CPA4 was significantly associated with TNBC phenotype, lymph node metastasis and stage, while it was not significantly correlated with age, grade or depth of invasion." (PMID 33746592, 2021).
thyroid cancer (2 papers, 2025). "The expression of Cpa4 is higher in human thyroid cancer than in normal and benign tissues and is associated with poor prognosis and dedifferentiation." (PMID 40076501, 2025). "Furthermore, knockdown of CPA4 abolished the ability of cells to develop xenograft tumor, suggesting that CPA4 stimulates the progression of thyroid cancer by mediating interactions between M2 macrophages and ATC cells and CPA4 can be a new therapeutic target for the treatment of patients with ATC." (PMID 40805261, 2025).
triple-negative breast carcinoma (2 papers, 2021 to 2023). An invasive breast carcinoma which is negative for expression of estrogen receptor (ER), progesterone receptor (PR), and human epidermal growth factor receptor 2 (HER2). "Moreover, a previous study has shown that CPA4 expression was detected specifically in the cytoplasm of cancer tissue cells, and in the CPA4-suppressed triple-negative breast cancer (TNBC), viability, and migration were decreased." (PMID 34827136, 2021).
anaplastic thyroid cancer (1 paper, 2025). "For example, in anaplastic thyroid cancer (ATC), CPA4 expression was upregulated in response to M2 macrophage stimulation." (PMID 40805261, 2025).
bladder urothelial carcinoma (1 paper, 2021). "The overexpression of Carboxypeptidase A4 (CPA4) has been observed in plenty of types of cancer and has been elucidated to promote tumor growth and invasion; however, its role in bladder urothelial carcinoma (BLCA) is still unclear." (PMID 34827136, 2021).
colon cancer (1 paper, 2016). "In this study, we firstly evaluated the expression of CPA4 in two different commercial tissue arrays containing 100 cases of colon cancer patients and 90 cases of rectal cancer patients with follow-up record." (PMID 27780921, 2016). "We speculated the possible reasons for the contribution of CPA4 to colon cancer liver metastasis." (PMID 27780921, 2016).
diabetic cardiomyopathies (1 paper, 2020). "Since CPA4 was associated with adipogenesis and insulin sensitivity, CPA4 may also participate in obesity-associated and diabetic cardiomyopathies." (PMID 32347291, 2020).
endometrial cancer (1 paper, 2025). Primary or metastatic malignant neoplasm involving the endometrium (mucous membrane that lines the endometrial cavity). "In endometrial cancer, CPA4 is significantly overexpressed, and gene set enrichment analyses have highlighted the estrogen signaling pathway among those associated with CPA4 expression." (PMID 40805261, 2025).
lung neoplasm (1 paper, 2013). A benign or malignant, primary or metastatic neoplasm involving the lungs. "On the other hand, long arm of chromosome 7 possesses imprinted domain in 7q32-qter which including MEST1, MESTIT1, COPG2IT1loci and a group of four carboxypeptidase A (CPA) genes (CPA1, CPA2, CPA4, CPA5), which are seem to be important (mainly MEST) in the initiation of breast and lung neoplasms." (PMID 23288724, 2013).